IL21 (interleukin 21)
Diseases named in the same sentence as IL21 in open-access papers (continued):
Sharing a sentence is not in itself a finding about the gene and the disease.
melanoma (continued). "In a syngeneic model of melanoma, IL-21 was used in combination with human (h)gp100, a melanocytic lineage differentiation antigen, to transduce DCs." (PMID 25961061, 2015). "Subcutaneous IL-21 also increased biomarkers of immune activation and one melanoma and two renal cancer patients obtained partial responses (out of 26 total patients)." (PMID 25961061, 2015). "Our study aimed at optimizing the antitumor effects of the B16F10/glycosylphosphatidylinositol-interleukin 21 (B16F10/GPI-IL-21) tumor vaccine on melanoma bearing mice by combining the TGF-β1 knockdown and the administration of miR200c agomir." (PMID 25895132, 2015). "Our previous study showed that administering whole tumor cell vaccine expressing IL-21 in the GPI-anchored form (B16F10/GPI-IL-21) induced protective anti-melanoma immunity in a B16F10 cell transplantable mouse model." (PMID 24625224, 2014). "Preclinical studies with IL-21 show inhibition of tumor growth in melanoma and RCC and anti-tumor cytotoxic activity in murine genetically modified IL-21 secreting tumors." (PMID 25268164, 2014). "Now, IL-21 has been used in phase I and II trials in cancer and early results demonstrated that recombinant IL-21 administration has an acceptable safety profile and has demonstrated encouraging activity in early phase renal cell carcinoma and melanoma trials." (PMID 25610441, 2014). "IL-21 is currently being evaluated in clinical trials as an immunotherapy agent against melanoma and renal cell carcinoma." (PMID 24669269, 2014). "CD8+ T cells obtained from IL-21 aAPC-expanded melanoma TIL cultures exhibited significantly higher cytotoxic activity compared with CD8+ T cells obtained from IL-15 and IL-2 aAPC expanded TIL." (PMID 23402380, 2013). "Lastly, IL-21 is currently used in phase I and II clinical trials in renal cell carcinoma, melanoma and non-Hodgkin's lymphoma with an overall good safety profile and encouraging single agent activity." (PMID 23853592, 2013). "The accuracy of the model was verified retrospectively under diverse IL-21 treatment settings, by comparing its predictions to independent “validation” data in melanoma and renal cell carcinoma-challenged mice (R2>0.90)." (PMID 22022259, 2011). "This new combined model was retrospectively and prospectively validated by in vivo experiments in IL-21-treated mice bearing melanoma (B16) or renal cell carcinoma (RenCa)." (PMID 22022259, 2011). "Ex vivo expansion of tumor specific lymphocytes using IL-15 and IL-21 produced fewer Tregs and more cytolytic cells against melanoma cell lines." (PMID 24281094, 2010). "Recent reports have revealed the effect of IL-21 in preclinical models, suggesting a strong antitumoural activity of IL-21 in renal cell carcinoma, melanoma and leukaemia." (PMID 18053164, 2007). "In three mouse tumor models (melanoma, glioma, colon carcinoma) Chen at al. showed that intratumorally administration of an IL-21-armed recombinant vaccinia virus, rTTVΔTK-IL-21, led to selective enrichment of immune effector cells at tumor site, long-lasting tumor regression and improved survival." (PMID 38638431, 2024). "Therefore, it was shown that IL-21 in combination with IL-15 enhanced the antitumor effect of CD8+ T lymphocytes leading to tumor regression in established melanoma." (PMID 38638431, 2024). "Moreover, using the B16-F10 melanoma model, the authors showed that IL-21 produced by in vitro differentiated Th17 cells also increases the frequency of CX3CR1+ CD8+ T cells in the tumor, which in turn was associated with reduced tumor burden." (PMID 33777008, 2021). "However, adoptive T cells stimulated with IL21 induced a more robust antitumor response in a murine melanoma model." (PMID 33381115, 2020). "Also, cells stimulated with IL-15 and IL-21 mediated enhanced immunity in mice with melanoma compared to T cells expanded in the presence of either IL-15 or IL-21 alone." (PMID 30842774, 2019).
melanoma (continued). "Moreover, upregulation of intracellular perforin was reported for CD56pos cells from HIV-infected individuals, from stimulated PBMCs and from patients with malignant melanoma upon IL-21 stimulation." (PMID 28659917, 2017). "The more recently discovered member of the γc cytokine family, IL-21, has also been explored as an anti-cancer treatment and IL-21 monotherapy of thymoma and melanoma in mice has shown to result in improved CD8+ T cell-mediated anti-tumor responses with augmented long-term survival." (PMID 27656185, 2016). "In addition, in a model using murine B16 melanoma cells that were transfected to secrete IL-21, it was shown that local presence of IL-21 can also promote anti-tumor immunity by preventing IL-2-mediated Treg induction." (PMID 27656185, 2016). "Although tested in only one patient, superior MHC-I restricted anti-tumor effector activity of the IL-21 aAPC expanded CD8+ T cells could also be confirmed by IFN-γ secretion upon exposure to autologous melanoma cells." (PMID 23402380, 2013). "In the B16 melanoma system, we have now demonstrated in mammary carcinoma that culturing B/I-activated lymphocytes from tumor-sensitized mice in IL-7/15/21 results in a much higher yield of viable cells than those grown in IL-2, IL-21, IL-2/21 and even IL-7/15." (PMID 28146052, 2017). "A proportion of mice receiving melanoma vaccine co-expressing IL-21 and IL-7 developed vitiligo over time, which possibly suggested that breaking of topical peripheral tolerance to self-antigens, in this case melanocyte-associated antigens, could be achieved using this new vaccine formulation." (PMID 27571893, 2016). "Thus, treatment with IL-21 + low-dose IL-2 after the adoptive transfer of pmel Tg CD8+ T cells into mice with established B16 melanoma tumors (pmel Tg/B16 model) might yield anti-tumor effects comparable to or greater than those observed with IL-21+IL-15." (PMID 16772043, 2006). "For example, a novel vaccine targeting CD133(+) CD44(+) MSCs in melanoma, expressing a 6kDa early secretory antigenic target (ESAT-6) and secreting interleukin (IL)-21, significantly suppressed melanoma growth and metastasis in mice, extending survival." (PMID 39611156, 2024). "Combined administration of IL15 and IL21 had synergistically accelerated the growth of both naive and memory CD8 T cells and resulted in tumor regression in a murine model of melanoma." (PMID 33381115, 2020). "Results are awaited from clinical trials evaluating the safety and efficacy of combining IL-21 with other immunotherapeutic agents (IL-21/Anti programmed cell death 1 [PD-1] against solid tumors/NCT01629758, IL-21/ipilimumab against melanoma, NCT01489059)." (PMID 30805309, 2019). "In this context and encouragingly, the effectiveness of the combination of ACT with IL-21-primed polyclonal cytolytic T cells and anti-CTLA-4 antibody in a melanoma patient that had failed prior treatments with ACT and anti-CTLA-4 has recently been reported." (PMID 28497159, 2017). "A combination of IL-18 and IL-21 has been used in clinical trials on NHL and melanoma; the regimens were well tolerated and provided significant clinical benefits." (PMID 25686210, 2015). "The combination of IL-21 and IL-15 was also administered IP subsequent to human gp10025–33 (hgp10025–33) peptide vaccination of lymphopenic, tumor-bearing (B16F10 melanoma) C57BL/6 mice." (PMID 16772043, 2006). "Herein we describe the long-term curative effect of combined IL-21 + low-dose IL-2 cytokine therapy in lymphopenic, tumor-bearing C57BL/6 mice infused with naive pmel splenocytes and vaccinated with the hgp10025–33 melanoma peptide." (PMID 16772043, 2006). "We also assessed expression of activation-responsive immune genes TNF, IL21, IL10, IL13, and CFS2 in the ICB melanoma dataset, and found that IFNG, TNF, and interleukins IL21 and IL10 seemed to increase upon treatment in responders, even though they were not differentially expressed." (PMID 32471032, 2020).
melanoma (continued). "In addition, co-administration of IL-21 and IL-15 enhanced the expression of IFN-γ by CD8+ T cells and induced melanoma tumor regression." (PMID 28927416, 2017). "An early report showed that IL-21 cooperates with IL-15 to promote the in vitro growth of both memory and naive mouse CD8+ T cells and in vivo expansion of antigen-specific CD8+ T cells mediating B16 melanoma regression." (PMID 25961061, 2015). "The study recruited dogs with histopathological diagnoses of oral malignant melanoma, generated their peripheral blood mononuclear cells, expanded them into predominantly non-B non-T cells via stimulations of IL-15, IL-2, and IL-21, and then re-infused the cells into tumor-bearing dogs." (PMID 38668417, 2024). "However, for a B16-F10 subcutaneous melanoma model combinatorial therapy of IL-21 and CTLA-4 or PD-1 resulted in smaller tumors without complete regression in any of the mice used for experiments." (PMID 38638431, 2024). "IL-21 has been studied in preclinical models of cancer pertaining to the maintenance of antigen-specific CD8 T-cell responses, as well as in relation to the proliferation, survival and functionality of cancer-specific T cells isolated from patients with melanoma or pancreatic cancer." (PMID 29854291, 2018). "This study examined whether recombinant IL-21 alone or in combination with low-dose IL-2 could improve the in vivo anti-tumor function of naïve, tumor-antigen specific CD8+ T cells in a gp10025–33 T cell receptor transgenic pmel murine melanoma model." (PMID 16772043, 2006).
inflammatory bowel disease (41 papers, 2007 to 2026). A spectrum of small and large bowel inflammatory diseases of unknown etiology. "The study of early onset of inflammatory bowel disease in patients deficient for IL-21 has advanced the understanding of IL-21 as a proinflammatory cytokine." (PMID 32991326, 2020). "Phosphorylated STAT3 then dimerizes, translocates, and binds to DNA, resulting in the production and release of inflammatory factors IL-17, IL-21, and IL-22, collectively influencing inflammatory bowel diseases like UC." (PMID 40446056, 2025). "Previously, increased levels of CD4+ T cells-derived IL-2 and IL-21 have been reported in inflammatory bowel disease." (PMID 31936604, 2020). "Studies have found that there is a high expression of IL-21 in most patients with inflammatory bowel disease, indicating that IL-21 plays an essential role in the process of inflammatory bowel disease." (PMID 32855360, 2020). "Several observations indicate that IL-21 can contribute to the detrimental response in inflammatory bowel disease-related inflammation." (PMID 28066428, 2016). "More than 50% of IL-21 producing Th cells co-express IFN-γ, thus confirming our previous studies showing that IFN-γ-expressing cells are a major source of IL-21 in the colon of patients with inflammatory bowel disease." (PMID 25839161, 2015). "Further, they demonstrated that IL-21 knockout mice were protected against DSS induced inflammatory bowel disease." (PMID 21959034, 2011). "IL-21 may trigger gut inflammation and plays a role in inflammatory bowel disease, while claudin-5 is a downstream gene of this cytokine." (PMID 36256663, 2022). "A role for intestinal CXCR5+ Th cells in sustaining cell-mediated immunity and inflammation, most likely through secretion of IL-21, has been supported by experimental animal models as well as in expression analyses of material from patients with colorectal cancer and inflammatory bowel disease." (PMID 35355990, 2022). "IL-21 plays a vital role in the progression of inflammatory bowel disease caused, but its mechanism is still not very clear." (PMID 32855360, 2020). "Previous studies have confirmed that in the process of inflammatory bowel disease, parasite infection, and other diseases, IL-21 stimulated T cell proliferation, promoted Th1 cell differentiation, increased the production of interferon (IFN)-γ, and aggravated the progression of inflammation." (PMID 32855360, 2020). "IL-21, a T-cell–derived cytokine, is produced in excess in inflammatory bowel diseases, which can be highly expressed in intestinal mucosa of IBD patients." (PMID 33584264, 2020). "IL-21 is overproduced in many chronic inflammatory disorders, including inflammatory bowel diseases (IBD), rheumatoid arthritis, and SLE." (PMID 28066428, 2016). "During inflammatory bowel disease (IBD), immune cells upregulate the secretion of IL-17, IL-21, IL-22, and IL-23 cytokines in the intestinal mucosa." (PMID 34207946, 2021). "In colonic biopsies from patients with inflammatory bowel disease (IBD), SIRT1 was downregulated by TNF-α and IL-21 in the mucosa." (PMID 33414704, 2020). "Serum level of IL-21 is increased in patients with inflammatory bowel diseases (IBD), suggesting that IL-21/IL-21 receptor (IL-21R) signaling may be involved in the pathogenesis of IBD." (PMID 27545302, 2016). "Similarly, the populations of IL-21–, IFN-γ–, and IL-17–producing CD4+ T cells are increased in patients with inflammatory bowel disease (IBD), including both CD and ulcerative colitis, compared with healthy controls." (PMID 35503415, 2022). "IL-21 is overproduced in inflamed gut of patients with inflammatory bowel disease compared to non-inflamed and inflamed controls." (PMID 28066428, 2016). "Nevertheless, how IL-21 is regulated in inflammatory bowel disease is not fully understood." (PMID 28066428, 2016).
inflammatory bowel disease (continued). "In human material, IL-21 and IL-21R expression was investigated by in situ hybridization (ISH) and immunohistochemistry (IHC) in noninflammatory bowel disease (non-IBD) controls and patients with CD." (PMID 29849593, 2018).
diabetes (36 papers, 2008 to 2025). "Emerging evidence has showed that numerous cytokines, including TGFβ, IL-6, IL-1β, and IL-21, are associated with bone remodeling in diabetes." (PMID 35993048, 2022). "Two of the lines were monitored for diabetes development and proved to be completely protected from the development of diabetes as expected based on prior studies of NOD mice deficient in IL-21 signaling." (PMID 33916486, 2021). "Type I diabetes susceptibility locus known as insulin-dependent diabetes susceptibility 3 (Idd3) encodes cytokine gene IL-21 and regulates diabetes." (PMID 25126585, 2014). "Deficiency in either IL-18 or IL-21 prevents the onset of diabetes in NOD mice." (PMID 33603744, 2020). "Within islet immune infiltrates, we demonstrated antigen-specific multifunctional IL-21+IFN-γ+CD4+ Tfh cells that were enriched in ICI-treated mice with diabetes." (PMID 40626363, 2025). "In mouse models of diabetes, blocking IL-21 signaling protected against the development of the disease." (PMID 38887289, 2024). "SUMO-defective c-Maf transactivated Il21, resulting in increased levels of IL21 in T cells, resulting, in turn, in the induction of diabetes." (PMID 34336833, 2021). "c-Maf SUMOylation in CD4+ T cells has been shown to regulate IL-21-mediated diabetes in NOD mice in an inverse manner." (PMID 34336833, 2021). "In a TCR transgenic mouse model of diabetes, T cells responding to islet antigen showed a Tfh phenotype with high IL-21 expression, and the pancreas-infiltrating T cells were shown to express IL-21, IFNγ, and TNFα." (PMID 35156097, 2021). "Recent data provides a compelling case for IL-21 as a critical immune regulator of T1D pathogenesis, since IL-21 and IL-21R deficient NOD mice are almost completely protected from diabetes, depending on the animal house." (PMID 31653894, 2019). "IL-21 neutralisation has been shown to prevent diabetes in mice, and a C-peptide-sparing benefit of anti-IL-21 alone or in combination with the glucagon-like peptide-1 (GLP-1) receptor agonist (RA) liraglutide has been observed in a clinical proof-of-concept study, as described further below." (PMID 33595677, 2021). "Similarly, IL-21 is critical for the development of T1D in NOD mice and NOD mice deficient in IL-21 receptors were protected from diabetes." (PMID 33343569, 2020). "Diabetes incidence in female NOD8.3/IL21R mice was significantly lower than wildtype NOD8.3 mice, in accordance with the previously observed protection in IL-21 or IL-21R deficient NOD mice." (PMID 31653894, 2019). "Whereas it has been shown that IL-21 can inhibit DC maturation, other studies suggested IL-21 can enhance DC function, and recent analysis has identified a role for IL-21 in triggering DC migration in a virus-induced diabetes model." (PMID 24470500, 2014). "Priming with interleukin-21 enables autoreactive CD8+ T cells to respond to weak antigens and may induce the diabetes onset in susceptible NOD mice." (PMID 24154763, 2013). "The decreased number of effector T cells we observed in IL-21R deficient mice underlies the protection against diabetes in the absence of IL-21 signaling." (PMID 18773086, 2008). "In this study, we found that IL-21 promotes insulitis and diabetes in NOD mice." (PMID 18773086, 2008). "Furthermore, IL-21 overexpression in pancreatic β-cells led to increased expression of inflammatory mediators such as IL-17A, IL-17F, IFN-γ, MCP-1, MCP-2, and IP-10, whereas IL-21R deficiency conferred protection against insulitis and diabetes in NOD mice." (PMID 40979706, 2025). "Blocking interferons on their own does not prevent diabetes in knockout NOD mice, so we tested whether JAK inhibitor action on signaling downstream of common γ chain cytokines, including IL-2, IL-7 IL-15, and IL-21, may also affect the progression of diabetes in NOD mice." (PMID 33343569, 2020).